IL7 (interleukin 7)
Diseases named in the same sentence as IL7 in open-access papers (continued):
Sharing a sentence is not in itself a finding about the gene and the disease.
tumor (continued). "Although other studies have shown that high NLR was related to the increasing of monocyte chemotactic protein-1, interleukin-1 receptor α (IL-1R-α), IL-6, IL-7, IL-8, IL-12 and IL-17 in peripheral blood, these cytokines could build and keep an immune microenvironment promoting tumor invasion." (PMID 28036275, 2017). "Next to IL-2, other γc-cytokines, such as IL-7, IL-15, and IL-21, have been described to play a role in memory T cell formation, proliferation, and survival, yet result in a lower degree of T cell differentiation but are still able to enhance anti-tumor responses." (PMID 27656185, 2016). "Because of the promising results seen with IL-21 to date, we endeavored to discover whether B/I and IL-21 exposure alone or in combination with IL-7/15 would increase the expansion of naïve or antigen-sensitized T cells, and whether it would increase anti-tumor activity." (PMID 25903148, 2015). "Furthermore IL-7 can enhance anti-tumor immunity by antagonizing inhibitory networks: favoring Th17 differentiation, downregulating transforming growth factor (TGF)-β production, limiting TGF-β-associated signaling, and rendering the effector cells refractory to Treg cells." (PMID 24465710, 2014). "Therefore, the skewing of circulating CD8+ T cell pools toward CCR7−CD45RA+CD8+ T cell along with an elevated IL-7 level may represent another aspect of tumor derived immunosubversion mechanisms in human." (PMID 24465587, 2014). "Therefore, it is unlikely that IL-7 has a direct effect on the tumor." (PMID 24465710, 2014). "In order to assess whether signaling responses also were altered in tumor-infiltrating T cells in SLL/CLL and MZL, tumor samples were stimulated with IL-2, IL-7 and IL-15 for 15 minutes and phospho-protein levels were evaluated in the CD5+ CD20- T cell fraction." (PMID 23072591, 2012). "We hypothesise that the enhanced tumour cell proliferation is accompanied by inhibition of the TGF-β signalling pathway in the (human) tumour cells via various stromal-derived mouse cytokines such as IL7 and IFNG." (PMID 22045186, 2011). "Similarly, targeting molecules on tumor-specific T cells that are involved in the regulation of T cell survival and effector functions (e.g., IL-7, IL-15, activating antibodies to CD137, blocking CTLA-4) might translate into improved clinical outcomes." (PMID 24212804, 2011). "IL-12 and IL-7 were utilized in the induction phase of the tumor-specific T cell response in vitro, because of the known function of IL-12 in directing the acquisition of strongly anti-tumor Th1/Tc1 effector functions, and of IL-7 in supporting the growth of human CD8+ T cells." (PMID 20711505, 2010). "To determine whether VEGFR-2 expression on pCSCs is regulated by tumor environmental cues, we examined the effects of cytokines on the expression in vitro., including Flt3 ligand (FL), GM-CSF, IL-3, IL-4, IL-6, IL-7 and IL-13." (PMID 18286204, 2008). "The increased IL-7 serum level may depend on immune system activation against the tumour." (PMID 18978943, 2008). "As previously demonstrated, CD8+ cells synchronously cultured in the presence of IL-2 plus IL-7 for 50 days and expanded to 108-fold demonstrated minimal efficacy against subcutaneous tumors (P = 0.39 versus control) with 1/5 mice achieving complete tumor regression." (PMID 15566571, 2004). "Recently, several groups have reported that transgenic expression of IL-7, either alone or with co-expression of CCL19, in CAR-T cells has resulted both in enhanced CAR-T cell persistence and in improved anti-tumor response." (PMID 41550947, 2025). "We also observed that IL-7 increases S1PR1 transcription in human CD8+ T cells, which we have shown to be protective against tumor-induced T cell sequestration." (PMID 40244705, 2025). "RJW-58 exhibited an anti-tumor activity and altered the expression of multiple cytokines in the serum of C57BL/6JNarl mice, with IL-7 being a significant factor." (PMID 40707961, 2025).
tumor (continued). "High IL-7 levels inhibit STAT5 phosphorylation and nuclear translocation, reducing CD4+T cell proliferation and impairing their anti-tumor immune function, thereby promoting PDAC development." (PMID 39958351, 2025). "In conclusion, we find that expansion of autologous T lymphocytes with IL-7 enhances the ability of CD8+ T cells to accumulate within intracranial glioma, even in the setting of tumor-imposed T cell sequestration." (PMID 40244705, 2025). "To boost the anti-tumor activity of these cells, we designed a second-generation CAR structure targeting EGFR that incorporates the full human IL-7 sequence." (PMID 41450878, 2025). "The results of the IHC consistently showed lower CTSS expression, higher IL-7 expression, and more infiltration of CD8+ T cells in tumor tissue samples from the treatment groups than in the control group." (PMID 40707961, 2025). "In contrast, IL-7 and CCL19 increase T cell infiltration and trafficking into tumor sites, which is often impaired in the TME, as demonstrated in solid tumor and lymphoma models." (PMID 40771804, 2025). "Recombinant NDV LX/IL (15 + 7), which co-expresses IL-7 and IL-15, enhanced the infiltration of CD8+ and CD4+ T cells, significantly inhibiting tumor growth in melanoma." (PMID 41479917, 2025). "Regarding administered (exogenous) ALT CD8+ T cells, IL-2 ALT in tumor also predominantly consisted of TEFF cells, while IL-7 ALT consisted of a mixed central/effector (TCM/TEFF) population." (PMID 40244705, 2025). "This suggests that the synergistic effect of GM-CSF and IL-7 can simultaneously enhance the mobilization of immune cells and long-term accumulation of memory T-cells in the TME, resulting in a sustained anti-tumor effect." (PMID 40299475, 2025). "Of the three candidates, Interleukin-7 (IL-7) has been reported to promote the cell death of immune cells through continuous signaling, while Serine proteinase inhibitor 9 (SERPINB9) mediates tumor immune evasion by inhibiting apoptosis of cancer cells." (PMID 41035689, 2025). "Fourth-generation CARs that incorporate cytokines (IL-7, IL-15, or IL-21) increase CAR-T-cell persistence, tumor targeting, and antitumor activity." (PMID 41019073, 2025). "By incorporating IL-7, the CAR-T cells exhibited enhanced proliferation and persistence, thereby improving their anti-tumor activity." (PMID 41450878, 2025). "To improve the phenotype of tumor-directed T-cell therapy, we show that provision of cell-intrinsic IL7R-mediated signaling is preferable to activation of cells with exogenous IL7." (PMID 39186002, 2024). "Together with the current result showing a skewed TCR clonality, it is suggested that IL7 and CCL19 produced by 7 × 19 CAR-T induce accumulation and proliferation of CAR-negative T cells expressing limited TCR with a reactivity to tumor antigens." (PMID 39240078, 2024). "We also investigated the immune microenvironment, finding high expression of IL7 in tumor cells and high IL7R expression in tumor-infiltrating T cells, suggesting that immune interactions also play a role in local tumor invasion and progression." (PMID 39093440, 2024). "Our results revealed that when LIPUS irradiated normal mouse for 14 and/or 21 days, even at day 30 after inoculation with 4 T-1 tumors, LIPUS promoted the release of some critical cytokines such as IL-2, IL-7 and IFN-γ in the plasma of tumor-bearing mice." (PMID 38349555, 2024). "For example, IL-7-producing immunotherapy improves the ex vivo T cell functions of immunosenescent patients, and IL-7 can sustain the CD27/CD28 expression and proliferative capacity to restrain tumor-induced T cell senescence." (PMID 39684260, 2024). "IL7 has been reported to inhibit TDT expression and IL7 treatment decreases TDT expression in two out of three stable tumor-derived cell lines." (PMID 38620028, 2024).
tumor (continued). "In this regard, fourth-generation CARs (referred to as “armored” CARs) that incorporate cytokines (IL-7, IL-15, or IL-21) are being developed to improve CAR-T cell persistence, tumor targeting, and antitumor capacity." (PMID 38191529, 2024). "CAR-T cells armed with IL-7 prolong the persistence of CD4+ T cells and enhance the anti-tumour response." (PMID 38675377, 2024). "GPC3-CAR-T cells were engineered to express IL-7 and CCL9 for stimulating the proliferation and facilitating migration, which effectively eradicated the tumor." (PMID 39569202, 2024). "The results of the study showed that combined treatment with IL-7 and IL-15 induced the recruitment and activation of TIL-Ts, which disrupted tumour cell growth and ultimately led to the regression of the primary osteosarcoma." (PMID 38675377, 2024). "Although mice in all treatment groups eventually had tumor growth, the combination of CAR+dex+IL-7 led to significantly prolonged survival over either the CAR+IL-7 group or the CAR+dex group." (PMID 38140726, 2024). "As a cytokine involved in T cell activation, maintenance, and proliferation, IL-7 enhanced CAR T cell effectiveness in vivo and facilitated tumor cell killing." (PMID 38693513, 2024). "However, it is important to note that IL-7/IL-7R-mediated signaling may exert pro-tumor functions." (PMID 38424167, 2024). "This construct co-expressed CXCR5 and IL-7 (C5/IL7) within the conventional NKG2D-CAR backbone, addressing both challenges, i.e., effective tumor penetration and sustained presence." (PMID 39450160, 2024). "In the adjuvant setting, tumor-bearing mice treated with dex and IL-7 post-CAR T cell infusion had superior survival outcomes compared with mice treated with dex or IL-7 alone after CAR T cell infusion in both dex-sensitive and dex-insensitive tumor models." (PMID 38140726, 2024). "We next investigated IL-7-secreting CAR-T-cell behavior and efficacy against tumor cells using an in vitro long-term tumor challenge model." (PMID 39093440, 2024). "In order to optimize therapeutic effectiveness, CAR-T cells expressing cytokines like IL-7 and chemokines like CCL19 have been engineered, significantly enhancing their anti-tumor capabilities." (PMID 38791916, 2024). "When IL-7 was combined with CAR-T cells in relapsed and refractory haematological malignancies, tumour growth was significantly inhibited." (PMID 38675377, 2024). "IL-7 and TGF-β act antagonistically, and the inhibition of TGF-β enhances the anti-tumour immune response, thereby inhibiting tumour growth." (PMID 38675377, 2024). "Intratumoral injection of CAR-GPC3 T cells secreting IL-7 and CCL19 resulted in complete tumor regression of an advanced HCC patient." (PMID 38679698, 2024). "MSCs are able to deliver a variety of cytokines and growth factors to the tumor site that were identified as anti-tumor agents, comprising IFN-α, IFN-β, IFN-γ, IL-2, IL-7, IL-12, IL-15, IL-18, IL-25, and NK4, an antagonist of HGF." (PMID 37686315, 2023). "We studied the γc cytokines IL-2, IL-7, IL-15 and IL-21 or IFN-γ, as these cytokines have been shown to stimulate anti-tumor immunity." (PMID 37923822, 2023). "The exception is one experiment that found the co-expression of IL-7 and CCL19, a chemoattractant for T cells and DCs, in CAR-Tcells can extend cell survival and enhance the anti-tumor efficacy of CAR-T cells in mice." (PMID 36936961, 2023). "Although CBD–IL-12 monotherapy–treated mice had significant elevation of certain markers, combination with IL-7–CBD increased the breadth and the magnitude of the cytokine secretion within the tumor." (PMID 38019919, 2023). "Reduced access to the homeostatic cytokines IL-7 and IL-15, critical for memory CD8+ T cell survival and maintenance, negatively impaired anti-tumor effector CD8+ T cell responses." (PMID 37426658, 2023).
tumor (continued). "Intratumoral treatment with IL-7–CBD + CBD–IL-12 led to a similar extension in survival in mice receiving FTY720 or vehicle control, pointing out that tumor-resident T cells are sufficient to drive the antitumor response." (PMID 38019919, 2023). "We then quantified secreted Flt3L and IL7 when CAR T cells were cultured alone or co-cultured with either CT2A-EGFRvIII-Luc (vIII), CT2A-GFP-Luc (2A) or 50% vIII and 50% 2A (vIII+2A) tumor cells." (PMID 36817432, 2023). "Transgenic IL-7 expression in CAR-T cells has therefore been explored and proven to increase tumor-targeting and killing in the presence of regulatory T cells in hematological and solid tumors." (PMID 37064017, 2023). "The SINV IL-12/IL-7-treated groups exhibited weaker luciferase signals compared to the control groups, which indicated that SINV can significantly reduce tumor size." (PMID 37835433, 2023). "Three-dimensional tumor models consisting of 624-MEL cells were co-cultured with human peripheral blood lymphoid cells (PBLs) in presence of the cytokines IL-2, IL-7, IL-15, IL-21 and IFN-γ." (PMID 37923822, 2023). "IL7 exerts its biological functions primarily by activating the IL7 receptor (IL7R) to mediate various signaling pathways and shape tumor immunity." (PMID 37958451, 2023). "We also showed significantly increased IL-6, IL-7, and GM-CSF levels in the supernatants of CAR133-i502-NK92 cells co-cultured with tumor cells." (PMID 37731205, 2023). "At 7 days after U-87MG-Luc cells were implanted into the CPu of the mice, the mice received intratumoral injections of SINV IL-12/IL-7 or PBS, followed by animal imaging at 21 dpi to evaluate tumor growth." (PMID 37835433, 2023). "To understand the mechanism of action and the therapeutic benefit of the addition of IL-7–CBD to CBD–IL-12, we performed spectral flow cytometry to provide an in-depth look at the tumor-infiltrating lymphocytes." (PMID 38019919, 2023). "Firstly, we established a subcutaneous tumor model in mice using the U-87MG-Luc cell line by randomly grouping the mice and intravenously injecting them with 100 μL of SINV IL-12/IL-7 (1.0 × 107 PFU) on days 7, 9, and 11 after cell transplantation." (PMID 37835433, 2023). "IL-2 CAR T cells were robust in killing tumor cells both in vitro and in vivo, but overtime CAR T cells expanded in IL-7/15 outperformed IL-2 CAR T cells with increased expansion and improved persistence." (PMID 35493513, 2022). "Compared with traditional CAR-T cells, IL-7 and CCR2b co-expressing CAR-T cells boosted self-survival and migration, enhanced IFN-γ, Gzms-B, and IL-2 expression, and obstructed tumor growth." (PMID 36168626, 2022). "We next measured IL‐7 concentration by ELISA in a collection of PEs from patients with MPM (n = 80), other neoplasia (n = 108) or benign pleural effusions (BPE) (n = 24)." (PMID 36054746, 2022). "Findings revealed a selective immune augmentation effect of IL-7 on CAR-T cells, including enhanced anti-tumor function, expansion, and persistence." (PMID 36419058, 2022). "Gene-engineering expressing IL-15 136, IL-7 and CCL19 137, and IL-4/21 138 has also been explored to boost anti-tumor activities through promoting proliferation, survival, activation, and stem cell memory subset of CAR-T cells and endogenous T cells." (PMID 36168626, 2022). "CAR T cells engineered to constitutively secret IL-7 and CCL19, recreating the T cell zone in lymphoid organs within the tumor, improved anti-tumor immunity in murine solid tumor models." (PMID 36366354, 2022). "To investigate cytokine secretion profiles of 28z/IL-7-CAR-T cells against Raji cells, we measured the IFNγ and TNFα response after co-culturing with tumor cells using flow cytometry." (PMID 35869100, 2022). "When MSCs that can release IL-7 and IL-12 are used in combination with CAR-T cells, CAR-T cells survive longer and have better expansion ability in vivo, thereby improving the anti-tumor response." (PMID 36238297, 2022).
tumor (continued). "Simultaneous expression of IL-7 and CCL19 in TCR T (7 × 19 P1A T) cells by genetic engineering can enhance the anti-tumor activity of TCR T cells by eliminating tumors and promoting long-term survival of mice." (PMID 36142322, 2022). "When the chemokine CCL21 and IL7 was transduced into CAR-T cells, it significantly improved survival and infiltration of both CAR-T and dendritic cells in the tumor, leading to complete tumor remission." (PMID 35432319, 2022). "To further reveal the relationship between FR4 positive cells and tumor immune microenvironment, we used 90 ESCC data from the TCGA public database to analyze PD-1, PD-L1, IL-2, IL-7, and levels of IFN-γ and TNF-α." (PMID 35756495, 2022). "Herein, anti-CD19 CAR T cells engineered to secret IL-7 and CCL19 are used to treat diffuse large B cell Lymphomas (NCT04381741, NCT04833504), aiming at promoting tumor infiltration, accumulation, and survival of CAR T cells in cancerous tissue." (PMID 36366354, 2022). "TNF-α secretion by IL-7 stimulation was increased by in CD8+ cells from tumor and para-tumor tissue." (PMID 35850640, 2022). "We next sought to investigate the IL-7-secreting CAR-T cell behavior and efficacy against tumor cells using a long-term tumor challenge model in vitro." (PMID 35869100, 2022). "The expressions of serum CXCL13, ICAM-1, MCP-5, IL-7, and TNF-α in tumor-bearing mice treated with rAd-mIL-28B were lower compared to rAd-EGFP-treated mice (P < 0.05)." (PMID 35935577, 2022). "With this in mind, CAR-Ts engineered to produce CCL19 and IL-7 (CCL19-IL-7 CAR-Ts) can act in a similar fashion as fibroblastic reticular cells in terms of T cell and DC recruitment to the desired tumor sites to help amplify tumoricidal effects." (PMID 35634281, 2022). "Chimeric switch receptor were also designed by combining the IL-4R extracellular domain with the intracellular signaling domains of IL-7 or IL-21, resulting in CAR T cells with enhanced anti-tumor activity against IL-4+ tumors." (PMID 33746981, 2021). "The pro-inflammatory cytokine IL-7 was downregulated in HGG, pointing towards a possibly insufficient immunosurveillance by lymphocyte infiltrates within the tumor." (PMID 34654395, 2021). "Although FRC growth or loss seems tumor specific, most data show that FRCs are reprogrammed by tumor cells to influence normal immune cell composition in TDLNs, and that CCL21 and IL-7 are critical to these changes." (PMID 33808959, 2021). "In head and neck carcinoma, other paracrine cytokines secreted by MSCs, including IL-6, IL-7, IL-8, and growth factors such as VEGF, have also been reported to be involved in the development of tumor drug resistance." (PMID 34095111, 2021). "The CAR-T cells engineered to express IL-7 and CCL19 have been validated to increase the infiltration of peripheral CAR-T cells and dendritic cells and into tumor tissues and enhance the anti-tumor immune responses." (PMID 34790207, 2021). "Nevertheless, IL7-Fc treatment of immune-intact mice markedly expanded endogenous CD8+ T cells in TLDNs and significantly increased the tumor-infiltration of endogenous CD8+ T cells." (PMID 34440787, 2021). "As targeting activated oncogenes is generally more tractable than tumour suppressors the biological pathways of most relevance for ALL are RAS/RTK and IL7 signalling." (PMID 34753926, 2021). "In fact, new generation of CAR-T cell has been engineered to expressed IL-7 and CCL19 to elevate anti-tumor efficacy." (PMID 34544443, 2021). "When tumor-bearing and CTX-treated mice received IL7-Fc under two different conditions: low-dose multiple injections vs. high-dose single injection, the repopulation of CD45+ cells was found to be continuously accelerated by both conditions." (PMID 34440787, 2021).